TGFA (transforming growth factor alpha)
Diseases named in the same sentence as TGFA in open-access papers (continued):
Sharing a sentence is not in itself a finding about the gene and the disease.
pancreatic cancer (continued). "In one report, strong TGFα immunoreactivity was found in 95% of pancreatic tumors, whereas EGF immunoreactivity was observed in only 12% of the tumors." (PMID 16822304, 2006). "In addition, a 6 kDa soluble form of TGFα, secreted by pancreatic cancer cell lines, was also detected in the culture media." (PMID 40410803, 2025). "In the case of the studies herewith reported, the in vitro and in vivo results demonstrate the potent antitumor activity of ADC that target TGFα, providing a strong rationale for further preclinical and clinical investigation of ADCs targeting proTGFα as a therapeutic strategy for pancreatic cancer." (PMID 40410803, 2025). "The fact that TGFα may have a role in the development of pancreatic cancer, together with its structural properties as a membrane-bound protein, opens the possibility of targeting this growth factor with therapeutic purposes." (PMID 40410803, 2025). "The ability to rescue proliferation by reintroducing TGFα also highlights its potential as a therapeutic target, where inhibiting TGFα function could provide a means to stymie pancreatic tumor growth." (PMID 40410803, 2025). "Here, we demonstrate that expression of TGFα facilitates proliferation of pancreatic cancer cells." (PMID 40410803, 2025). "The observed overexpression suggests a potential role of TGFα in pancreatic tumor progression." (PMID 40410803, 2025). "Moreover, the role of TGFα in pancreatic cancer progression is not only restricted to enhancing cell proliferation but also involves its effect on the tumor microenvironment." (PMID 40410803, 2025). "The presence of TGFα in pancreatic cancer was not limited to its overexpression." (PMID 40410803, 2025). "TGFA is highly expressed in tumor tissues such as bladder cancer, oral cancer, pancreatic cancer, and small cell lung cancer, accelerating cell proliferation, invasion, and EMT (epithelial–mesenchymal transition), and is closely related to the prognosis of tumor patients." (PMID 35774505, 2022). "It was found that TGFA was widely involved in the signaling pathways (PI3K-AKT pathway, Hepatocellualr carcinoma, Pancreatic cancer) from KEGG and was significantly upregulated in PAAD patients (n = 178) than the normal samples (n = 171, P<0.05)." (PMID 33661995, 2021). "Moreover, reintroduction of TGFα into TGFA-knockout cells restored their proliferative potential, further corroborating the centrality of this growth factor in pancreatic cancer progression." (PMID 40410803, 2025). "Since TGFα acts as one of the ligands of the EGFR, and the pancreatic cancer cell lines expressed the receptor, we reasoned that coexpression of the EGFR could facilitate the antiproliferative action of the anti-TGFα ADCs." (PMID 40410803, 2025). "However, no pancreatic tumor was detected after prolonged TGFα induction beyond one year in both models." (PMID 25803032, 2015). "Similarly, carcinogen-induced pancreatic cancer in the hamster and rat expressed only TGFα and EGFR, but not EGF." (PMID 16822304, 2006).
colorectal cancer (27 papers, 1990 to 2025). A primary or metastatic malignant neoplasm that affects the colon or rectum. "In colorectal cancer cells and cell lines from tumours of the head and neck, overexpression and secretion of TGFα were associated with cetuximab resistance." (PMID 27933395, 2017). "For example, autocrine production of the EGFR ligand TGFA was confirmed to be linked to an increased risk of developing metastasis in colorectal cancer, whereas a feedback activation of EGFR was responsible for the failure of BRAF inhibition in patients carrying the mutation BRAF(V600E)." (PMID 31052457, 2019). "While RHBDD1 promotes colorectal cancer (CRC) via TGFα/EGFR/ERK signaling, our study reveals a distinct mechanism in ESCC, where RHBDD1 enhances invasion by activating Wnt/β-catenin via ELK3." (PMID 40787199, 2025). "For instance, miR‐194 inhibited cell proliferation, migration, and invasion via decreasing transforming growth factor alpha in colorectal cancer." (PMID 32862492, 2020). "Overexpression of TGFα contributes to resistance to EGFR inhibitor cetuximab in colorectal cancer cells." (PMID 30034618, 2018). "Expression of TGFα, EGF, and EGFR worsens prognosis and increases the metastatic potential of breast, renal, and colorectal cancers, all known to be obesity-associated malignancies." (PMID 27525640, 2017). "EGFR immunoprecipitated together with MET in cetuximab-resistant colorectal cancer cells, and this interaction was also observed in parental cells by TGFα stimulation." (PMID 26318427, 2015). "Supportive evidence for the involvement of TGFα in metastasis comes from a recent study that identified TGFα as a member of the gene set that that identifies colorectal cancer cells that metastasize to the liver." (PMID 23986907, 2013). "In addition, ligands such as epidermal growth factor(EGF), transforming growth factor alpha(TGFα), and two‐regulator proteins have been found in the EV of breast and colorectal cancer cell lines." (PMID 39015555, 2024). "For example, in colorectal cancer, the expression of transforming growth factor α (TGFα) often leads to liver-only metastasis, whereas in prostate cancer, the expression of platelet-derived growth factor receptor beta (PDGFR-β) often leads to bone-only metastasis." (PMID 30103827, 2018). "One of the pathways involved in the carcinogenesis of colorectal cancer is the signaling pathway related to the activation of EGFR, for which the ligand is, inter alia, transforming growth factor-alpha (TGFα), which is formed with the participation of ADAM 10 and 17 proteins." (PMID 36286024, 2022). "Consistently, positive regulators of Akt signaling, such as Akt (Z-score = 1.626, p = 1.18E–06), IGF2 (Z-score = 2.025, p = 4.70E–10), TGFA (Z-score = 2.251, p = 1.96E–04), and MAPK8 (Z-score = 2.231, p = 4.01E–05), were activated in recurrent colorectal cancers." (PMID 33425893, 2020). "Full-length N-term-out functional EGFR ligands Amphiregulin (AREG), heparin binding EGF (HB-EGF) and transforming growth factor alpha (TGF)-α were first identified in sEVs derived from a panel of breast and colorectal cancer cell lines using fluorescence-activated vesicle sorting (FAVS)." (PMID 33228060, 2020). "Inhibition of the ligands instead of the receptors could be an effective alternative treatment because it was shown that the overexpression of EGFR ligands, for example, TGFA, correlates with poor survival in PDAC, colorectal cancer, bladder cancer or head and neck cancer." (PMID 37341059, 2023).
lung carcinoma (27 papers, 1990 to 2025). "Adding NTS to lung cancer cells increases the shedding of TGFα, which activates the EGFR, or neuregulin-1, which activates HER3." (PMID 37508387, 2023). "A positive correlation was observed between LASTR and TGFA expression level based data for lung cancer patients retrieved from the TCGA database (r = 0.26, P < 0.001)." (PMID 35281858, 2022). "Previous studies have reported that NUP37 promotes lung cancer cell proliferation and inhibits apoptosis, while the overexpression of TGFA and HPF induces cell proliferation and invasion in lung cancer." (PMID 35963622, 2022). "The findings of the present study showed that the lncRNA, LASTR plays an oncogene role in lung cancer through miR-137/TGFA/PI3K/AKT axis." (PMID 35281858, 2022). "Western blotting assay showed that the LASTR/miR-137/TGFA axis modulates activity of the classical PI3K/AKT signaling pathway to promote proliferation of lung cancer cells." (PMID 35281858, 2022). "The findings of the current study showed that the lncRNA, LASTR promotes lung cancer cell progression through a ceRNA mechanism (miR-137/TGFA axis)." (PMID 35281858, 2022). "Subsequent experiments showed that the LASRT significantly promotes lung cancer progression through the miR-137/TGFA/PI3K/AKT axis." (PMID 35281858, 2022). "Knockdown of LASTR considerably curbed the proliferation and metastatic ability of lung cancer cells through the miRNA-137/TGFA axis." (PMID 36249015, 2022). "Similar to our results with CSF1, in lung cancer cell lines, TGFα leads to an increase in tyrosine phosphorylation of Vav1, while depletion of Vav1 reduces TGFα expression." (PMID 25313137, 2014). "Depletion of Vav1 in lung cancer cells decreased expression of TGFα, an autocrine growth factor that activates these cells." (PMID 23342133, 2013). "The findings indicated that miR-137/TGFA is a downstream axis for LASTR activity in lung cancer." (PMID 35281858, 2022). "However, research has demonstrated that LASTR modulates the activity of the U4/U6 recycling factor SART3 to boost cancer fitness, and also modulates the activity of the miR-137/TGFA/PI3K/AKT axis to accelerate lung cancer progression." (PMID 36551318, 2022). "A previous study has reported that TGFA gene promotes progression of lung cancer cells." (PMID 35281858, 2022). "Further analysis was conducted to explore whether the lncRNA LASTR promotes lung cancer progression through a ceRNA mechanism (LASTR/miR-137/TGFA axis)." (PMID 35281858, 2022). "Also, diminished Vav1′s expression in lung cancer cell lines reduced the expression of the growth factors, TGFα and EGF, and CSF-1, which led to reduced tumorigenicity." (PMID 35326399, 2022). "Other highly significant features include sHER2/sEGFR2/sErbB2, AXL, TGFa, and FGF2, demonstrating strong predictive power in lung cancer classification." (PMID 40217526, 2025). "Dopeso reported that EMT-induced upregulation of TGFA can stimulate EGFR, activate SMAD pathway and induce EMT, which forces a positive feedback loop to enhance EMT and metastasis of lung cancer." (PMID 34150632, 2021). "In lung cancer cells, the expression of EGFR and their ligands, especially transforming growth factor-alpha (TGFα), signifies the presence of a self-stimulatory (autocrine) growth factor loop." (PMID 34830377, 2021). "To determine how frequently ligands that initiate signaling of both pathways are found in lung cancer, we analyzed serum for hepatocyte growth factor (HGF), transforming growth factor-alpha, and amphiregulin (AREG) in lung cancer cases and tobacco-exposed controls." (PMID 21390244, 2010).
ovarian carcinoma (25 papers, 1991 to 2025). A malignant neoplasm originating from the surface ovarian epithelium. "TGFα is upregulated in many tumors, and is associated with tumor invasion and metastasis, such as in hepatocellular, breast and ovarian cancer." (PMID 26843615, 2016). "The mitogenic action of TGFα has been implicated in growth, progression and outcome of epithelial ovarian cancer." (PMID 23155381, 2012). "TGFα present in effusions from cancer patients is also associated with tumor burden in patients with epithelial ovarian cancer." (PMID 23155381, 2012). "TGFα has been previously linked to ovarian cancer progression." (PMID 33069212, 2020). "Interestingly, TGFα is implicated in the growth and invasion of ovarian cancer cells via the activation of EGFR signaling." (PMID 30034618, 2018). "De novo expression of transforming growth factor-alpha (TGFa) is induced in omental stromal fibroblasts whereas tumor necrosis factor-alpha (TNFa) is expressed by ovarian cancer cells." (PMID 34206026, 2021). "In ovarian cancer cell lines, the downregulation of HSPB8 positively directs the migration progress of the transforming growth factor alpha (TGF-α) for ovarian cancer cells." (PMID 34235216, 2021). "For example, TGFα levels have been shown to be elevated in the ascites fluid of patients with stage III/IV ovarian cancer compared to stage I/II." (PMID 33069212, 2020). "For example, in a mouse model of ovarian cancer, tumor cell-derived TNFα induced omental fibroblasts to produce TGFα, which in turn stimulated ovarian cancer EGFR and accelerated metastatic potential." (PMID 33069212, 2020). "Although EGFR signaling pathways in ovarian epithelial cancer cells have been described, very little has been shown regarding the signaling pathways activated by TGFα and EGF in GCTs." (PMID 23155381, 2012). "In the present study we have tested its activity against five ovarian cancer cell lines in vitro to assess its growth inhibitory activity and its ability to inhibit TGFα activated EGFR phosphorylation in this disease." (PMID 11875715, 2002). "We observed good reversal of EGFR tyrosine phosphorylation produced by TGFα activation in ovarian cancer cell lines and this was consistent with growth inhibition at these concentrations." (PMID 11875715, 2002). "Ovarian cancers that express increased concentrations of the EGF receptor are associated with poor survival and both TGFα and EGF have been shown to stimulate growth of ovarian cancer cells in culture." (PMID 11875715, 2002). "Thus, a TNFa-TGFa-EGFR axis appears crucial for the peritoneal colonization of ovarian cancer cells." (PMID 34206026, 2021). "TGFα has also been shown to be involved in tumor cell/stromal cell interactions in ovarian cancer." (PMID 33069212, 2020). "Additionally, histological examinations of the epithelial portion of ovarian tumors and characterization of ovarian cancer lines have shown that some ovarian cancer cells produce TGFα, consistent with our findings here." (PMID 33069212, 2020). "With the aim to identify the upstream regulators of AREG and transforming growth factor-alpha (TGF-α) release, we focused our work on ADAM17, a metalloprotease, highly expressed in ovarian cancer and the major sheddase of these cell membrane hosted ligands." (PMID 29662625, 2018). "In conclusion, hub genes (such as TGFA, EGFR, ErbB2, and MYC) and key pathways (such as the ErbB signaling pathway) closely related to the proliferation of ovarian cancer cells in hypoxia were identified by bioinformatics analysis." (PMID 29482638, 2018). "EGFR ligands, including EGF, TGFα, and HB-EGF, have all been suggested to enhance ovarian cancer progression and increase tumor cell proliferation." (PMID 27888810, 2016).
ovarian carcinoma (continued). "For both breast and ovarian carcinomas, it has been shown that the increased release of various substrates such as AREG, transforming growth factor alpha (TGF-alpha), and HB-EGF activates the EGFR receptor and contributes to tumorigenesis and disease progression." (PMID 36497350, 2022). "Similarly, there are also examples of increased expression of TGFα in stromal fibroblasts by secreted TNFα from cancer cells and in-turn, stimulation of EGFR signaling in ovarian cancer cells by TGFα secreted from omental fibroblasts." (PMID 31426393, 2019). "The results show that hypoxia can promote the proliferation of ovarian cancer cells by affecting the invasion and adhesion functions through the dysregulation of ErbB signaling, which may be governed by the HIF-1α-TGFA-EGFR-ErbB2-MYC axis." (PMID 29482638, 2018). "Additionally, TGFα has been reported to regulate secretion of CA125, a common serum marker of ovarian cancer, and tissue plasminogen activator from human ovarian carcinomas." (PMID 23155381, 2012).
COVID-19 (23 papers, 2020 to 2026). A disease caused by infection with severe acute respiratory syndrome coronavirus 2. "As for TGFα, concentrations of this growth factor in plasma of COVID-19 patients with the Alpha variant were higher than in other variants." (PMID 36430621, 2022). "The presence of CASP3, EPCAM, KRT19, and TGFA in the red module therefore suggests that one of the key features of the post-COVID-19 airway is the presence of ongoing epithelial injury and repair." (PMID 35151371, 2022). "VEGF and TGFα levels were higher in LTBI/COVID-19 vs. COVID-19." (PMID 36090983, 2022). "The surviving severe COVID-19 patients showed significantly lower circulating concentrations of TNFα, TGFα, IL-10, sRAGE, sTNF-RI and sTNF-RII compared to the non-survivors (p = 0.001, p = 0.031, p < 0.0001, p < 0.0001, p = 0.001 and p < 0.0001, respectively)." (PMID 36142255, 2022). "In the critical COVID-19 group, the heatmap and volcano plot even showed that the levels of some circulating cytokines were marginally lower in patients with asthma than those without asthma, particularly on THPO, LTα, and TGFα." (PMID 34238349, 2021).